NRP1 (neuropilin 1)
Diseases named in the same sentence as NRP1 in open-access papers (continued):
Sharing a sentence is not in itself a finding about the gene and the disease.
tumor (continued). "To further examine the timing and location of NRP1 in PCa, we relied upon a publicly available single-cell RNAseq (scRNAseq) analysis of 13 tumour biopsies from 12 PCa patients, including those with luminal, basal, or proliferative phenotypes for details)." (PMID 36550208, 2023). "Flow cytometric tests have found rather low NRP1 levels in benign prostate epithelial cell lines and demonstrated elevated NRP1 levels in tumor cells with increased metastatic potential, with the highest expression found in mCRPC cells." (PMID 37371647, 2023). "The average decrease in xenograft tumour volume was 512.7 mm3, which represents a 30.97% tumour suppression rate due to knockdown of NRP1, and an average decrease in xenograft tumour weight of 47.34% to approximately 0.98 g." (PMID 37702613, 2023). "Emerging studies have reported the antitumor effects of anti-NRP1 and -NRP2, mediated by tumor-associated macrophages." (PMID 37190154, 2023). "MiR-320, which regulates tumor angiogenesis by targeting neuropilin 1, is decreased in vascular endothelial cells of OSCC tissues." (PMID 36737832, 2023). "NRP1 regulates tumor growth and vascular remodeling and modulates vascular permeability signaling pathways." (PMID 36834519, 2023). "An A7R (ATWLPPR) peptide selected by phage screening technology can target NRP-1 and is widely used in tumor-targeted therapy." (PMID 36902076, 2023). "A previous study reported that NRP1 is highly expressed in several tumors, and an increase in its level correlated with tumor progression, thus highlighting the crucial role played by NRP1 in the occurrence and development of cancer." (PMID 36841806, 2023). "A peptide that targets NRP-1 can inhibit tumor angiogenesis and metastasis by disrupting the interaction of NRP-1 with VEGF and other growth factors." (PMID 37601380, 2023). "Neuropilin 1 (NRP-1) is an important receptor in tumor angiogenesis that regulates this process by binding to ligand VEGF-A and activating downstream signaling pathways." (PMID 36902076, 2023). "Altogether, these findings point to an important NRP1/PKC axis that promotes tumour cell survival and docetaxel resistance." (PMID 36550208, 2023). "While expression of TGFβ-dependent and activation markers are higher in the tumor, Nrp1 and TCF1 are higher in the lymph node, as expected." (PMID 37552475, 2023). "Although NRP1 mainly modulates axon guidance and angiogenesis processes, recent evidence highlights the potential role of NRP1 in tumor progression and therapeutic failure, arising as a potential prognostic biomarker and therapeutic target." (PMID 36376373, 2023). "Due to its ability to interact with numerous growth factor receptors, such as VEGF/VEGFR, NRP1 has shown to modulate several signaling pathways involved in tumor progression." (PMID 36376373, 2023). "It was verified that EG10377, a specific inhibitor of NRP1 attenuated PCa progression, and demonstrated that targeting NRP1 with a genetic or small-molecule approach significantly inhibited PCa tumor growth." (PMID 36841806, 2023). "A role for NRP-1 (neuropilin-1) in mediating in vivo tumor uptake of the polyplex was demonstrated by preblocking with an antibody against NRP-1, which reduced tumor luciferase activity by 98%." (PMID 37298407, 2023). "Our results showed a positive correlation between Treg infiltration levels, and NRP1 and NRP2 expression was observed in PAAD, which partially revealed the immunosuppressive TME and poor prognosis of tumor patients with high expression of NRP1 and NRP2." (PMID 37190154, 2023). "iNGR initially bound to APN, with iNGR proteolytically cleaved to CRNGR, and then targeted NRP-1 to mediate deep penetration in the tumor parenchyma." (PMID 36762192, 2023). "The literature reveals great interest in neuropilin-1 in the context of the mediation of tumor development and progression, as its increased expression in the tumor vasculature has been observed." (PMID 37112459, 2023).
tumor (continued). "NRP1 can promote tumor angiogenesis, tumor cell migration and invasion, and the infiltration of immunosuppressive cells into the tumor microenvironment." (PMID 37072474, 2023). "As previously demonstrated, neuropilin-1 is the proper target on the surface of tumor vascular endothelium." (PMID 37280670, 2023). "For example, NRP1 on stromal myofibroblasts acts on soluble fibronectin to promote fibronectin fibril assembly and matrix stiffness, resulting in the stimulation of tumor growth." (PMID 37894289, 2023). "Further, the role of NRP1 in tumor growth and migration in the xenograft mouse model was investigated." (PMID 36841806, 2023). "SLC7A11 expression was positively associated with the expression of immune checkpoint genes (NRP1, TNFSF4, TNFRSF9, and CD276) and tumour mutation burden." (PMID 37919768, 2023). "In melanoma, Nrp-1+ Tregs migrate along a VEGF gradient into the tumor tissue and suppress anti-tumoral immune responses." (PMID 38019895, 2023). "Tumor progression is accompanied by a reduction in Tregs that produce NRP1, and NRP1 can partially mediate a reduction in Treg number and function induced by anti-angiogenic drugs." (PMID 37894289, 2023). "Blockade of Sema3A/Nrp1 signaling prevents macrophages from entering hypoxic tumor regions, inhibits angiogenesis and restores anti-tumor immunity." (PMID 37143720, 2023). "The cyclic form of RGD, the iRGD peptide, has increased tumor penetrating abilities compared to RGD due to its ability to efficiently bind the transmembrane glycoprotein neuropilin 1 (NRP-1) in addition to αvβ3 integrins." (PMID 37287910, 2023). "Whereas mice injected with NRP1-knockdown GBM cells survived significantly longer than the control, ectopic expression of TGF-βR1 T204D in NRP1-knockdown GBM cells restored tumor formation capacity." (PMID 37788099, 2023). "TPN had been described to increase intratumoral uptake through binding to integrins by tumor penetrating iRGD followed by proteolytic cleavage and initiation of transcytosis through a semaphorin receptor NRP1 which is highly expressed on tumor cells." (PMID 37490255, 2023). "We identified Nrp-1 to facilitate the migration of CD4+Foxp3+ Tregs into tumor tissues in response to VEGF." (PMID 38019895, 2023). "Early post-PDT phase: thanks to M2 targeting (high NRP-1 expression), the remaining macrophages will be of the M1 phenotype (in yellow), leading to tumor destruction." (PMID 36986856, 2023). "Increased NRP1 expression in human HCC tissue was also observed in this study, as well as higher NRP1 levels in advanced tumor stages and nodal metastasis status." (PMID 36376373, 2023). "Here, we used a large MB tumor dataset to examine NRP1 gene expression in different molecular subgroups and subtypes of MB." (PMID 37511358, 2023). "The cleavage activates the CendR motif to be able to interact with NRP-1 to trigger the internalization of the peptide/cargo into tumor cells." (PMID 37111665, 2023). "It was also confirmed by an independent analysis performed with the GSE14520 dataset, in which differential-expressed genes were determined, identifying a significant overexpression of NRP1 in tumor tissues compared to paired non-tumor tissues of HCC patients." (PMID 36376373, 2023). "Then, we showed that secreted SEMA3B inhibits tumor angiogenesis by competitively binding to NRP1 with VEGF and ultimately suppresses the proliferation, migration, and invasion of CRC cells." (PMID 37701532, 2023). "NRP1 is a potential molecule that can modify the tumor microenvironment (TME) and innate immune system in a targeted way to produce an efficient anti-tumor immune response, which binds to and uptakes neutrophil elastin on a number of BRCA cell lines." (PMID 36911389, 2023). "The iRGD peptide homes in on and penetrates the tumor through integrin αvβ3 and neuropilin-1 (NRP-1) mechanisms." (PMID 36839936, 2023).
tumor (continued). "The results revealed that the NRP1 inhibitor suppressed tumor growth (p < 0.001) and prolonged survival (p = 0.01) compared with those in the control group of immunocompetent C57BL/6 mice." (PMID 37190154, 2023). "Tumor angiogenesis and metastasis can be inhibited by disrupting the interaction of NRP-1 with growth factors such as VEGF." (PMID 37601380, 2023). "Further in vivo experiments revealed that the NRP1 inhibitor suppressed PAAD tumor growth and prolonged survival, and the effects were more pronounced in the immunocompetent C57BL/6 mouse model." (PMID 37190154, 2023). "When Nrp1 was knocked down in models of human epidermal squamous cell carcinoma tumors, epithelial cancer stem cell spheroid formation was inhibited; tumor formation was further reduced and cancer cell migration and invasion was inhibited." (PMID 36203599, 2022). "The findings presented in this study demonstrate that tumor angiogenesis and growth can be arrested completely by cotargeting endothelial NRP1 and NRP2." (PMID 36970722, 2022). "Along with this, the correlation of prognosis and other tumor-related parameters was evaluated with high NRP1 levels in either tissue or serum samples, increasing the uncertainty of the results." (PMID 35884516, 2022). "NRP-1 is overexpressed on various tumors, so NRP-1-dependent endocytosis results in enhanced tumor penetration providing low toxicity to normal cells." (PMID 36500454, 2022). "We further explored the potential mechanism by which solasonine influences tumor biology in BC and its effect on NRP1 expression in vitro." (PMID 35281516, 2022). "With specific respect to the tumor cell-specific interplay between Nrp1 and hypoxia, there is one study to our knowledge that has uncovered a specific interaction between Hif1a and Nrp1." (PMID 36203599, 2022). "We searched PubMed, Scopus, Web of Science, Embase and Cochrane Library databases for articles evaluating the NRP1 correlation with survival parameters, tumor development or clinicopathological features." (PMID 35884516, 2022). "For instance, the restriction of TAMs to normoxic regions by blocking the Sema3A/Neuropilin-1 pathway reduced tumor pro-angiogenic and immunosuppressive functions and inhibited tumor development and metastasis." (PMID 35574385, 2022). "VEGF can activate the neuropilin-1 receptor (NRP1), which is upregulated in the outermost population and promotes proliferation, migration and invasion of tumor cells." (PMID 35273957, 2022). "NRP1 is a tumor promotor overexpressed in several tumor tissues such as oral squamous cell carcinoma, breast and lung cancers." (PMID 35887311, 2022). "Targeted inhibition with an NRP1 monoclonal antibody reduced spheroid-forming capacity and potently suppressed tumor growth in an orthotopic claudin-low TNBC xenograft model." (PMID 35078508, 2022). "The “trans” state involves two different cells, a tumor cell (expressing Nrp1) and an endothelial cell (expressing VEGFR2)." (PMID 36203599, 2022). "Meanwhile, GPX8 mRNA expression was significantly correlated with monocyte marker CD14, dendritic-cell marker NRP1, natural killer cell marker B3GAT1, neutrophil marker CCR7, and tumor-associated fibroblast marker FAP." (PMID 36061208, 2022). "As a tumor-homing and penetrating peptide, iRGD has not only the properties of binding to neuropilin-1 and integrin αvβ3 but also internalizing into TNBC cells." (PMID 36199363, 2022). "NRP1 acts as a cell-surface receptor for Sema3A and affects cell survival and migration, which are essential for tumor progression and EMT." (PMID 35775491, 2022). "Finally, to exclude tumor size as a statistical confounder, and therefore assess whether the loss of endothelial NRP1 and NRP2 directly influences pathologic angiogenesis, tamoxifen administration was suspended further until 12 days after CMT19T cell implantation." (PMID 36970722, 2022).
tumor (continued). "The results showed that CD276, CD40, CD274, CD44, and NRP1 expression was exclusively upregulated in cluster 0 (invasive tumor)." (PMID 36685583, 2022). "The majority of Tregs, both entering and exiting the tumor expressed NRP-1, potentially suggest a thymic origin, although this requires further validation." (PMID 35472220, 2022). "In the present study, we found that NRP1 was significantly correlated with tumor pathogenesis and also with several clinicopathological features that place it as an interesting biomarker and target, respectively." (PMID 35884516, 2022). "In the tumor xenografts model, inhibition of STAT6 activation reduced tumor angiogenesis and NRP1 expression, suggesting the therapeutic potential of STAT6 inhibitors." (PMID 35600336, 2022). "NRP‐1 also interacts with α5β1 integrin at sites of EC adhesion to fibronectin and with β1 integrin subunit in tumour cells." (PMID 34252269, 2022). "The combination of cis and trans states describe expression of VEGFR2 on endothelial cells, while NRP1 is present on both endothelial and tumor cells (which is the most likely scenario)." (PMID 36203599, 2022). "NRP1/NRP2 knockout tumor vasculature was found to express significantly less VEGFR-2 than either NRP1 or NRP2 knockout tumors, in addition to reduced phosphorylated VEGFR-2 expression." (PMID 36970722, 2022). "Follow up genetic ablation of Nrp1 in microglia and macrophages phenocopy results seen by pharmacological inhibition of Nrp1, which all resulted in a decrease in tumor volume and vascularity." (PMID 36203599, 2022). "The mechanism by which Nrp1 is engaged in cells that had acquired resistance to targeted therapies seems to involve secretion of galectin-1 by treatment resistant tumor cells in an autocrine manner." (PMID 36203599, 2022). "Consistent with preclinical data obtained from orthotopic PDAC mice, expressions of PlGF/VEGF-A, VR1+CAF, and NRP1+CAF represented a statistically significant correlation with tumor fibrosis and PDAC patient prognosis." (PMID 36272973, 2022). "This trans localization of NRP1 with VEGFR2 ultimately suppresses tumor angiogenesis, reduces proliferation, and promotes patient survival." (PMID 36203599, 2022). "This route has been exploited artificially to deliver a drug payload to NRP1‐expressing cancer cells by attachment of an iRGD peptide to NRP1 and so initiate tumor cell killing." (PMID 36069030, 2022). "In tumor xenograft models, inhibition of STAT6 reduced xenograft growth, tumor angiogenesis, and NRP1 expression in vivo." (PMID 35600336, 2022). "iRGD favors particle extravasation and allows the interaction with integrin αvβ3 (αvβ3), αvβ5 and neuropilin-1 (NRP-1) present on tumor vascular and cancer cells." (PMID 36297407, 2022). "Critically however, dual loss of both NRP1 and NRP2 was found to reduce primary tumor growth and primary tumor angiogenesis by a greater extent than when either molecule was targeted individually." (PMID 36970722, 2022). "There are one AP1 element and two SP1 elements that contributed to constitutive and tumor promoter-induced promoter activity of NRP1 in HeLa cells." (PMID 35600336, 2022). "These highlights the interesting role of CD276 and NRP1 as therapeutic targets of a claudin-low subtype tumor unresponsive to the PD-L1 inhibitor." (PMID 36685583, 2022). "For example, by antagonizing the interaction between NRP1 and Sema3A, Pan and colleagues, demonstrated an inhibition of tumor angiogenesis and tumor growth in vivo, effects that were compounded when combined with antibodies directed against VEGF binding." (PMID 36970722, 2022). "This study showed that Semaphorin3a, which is induced by hypoxia, attracts TAMs to the hypoxic regions of the tumour through Nrp1, triggering PlexinA1/A4-dependent VEGF receptor 1 (VEGFR1) activation." (PMID 36497148, 2022).
tumor (continued). "Comparison between ACE2 and NRP1 revealed that expression level of NRP1 was higher than that of ACE2 in most tumor and normal tissues (including lung tissues and plasma)." (PMID 36338984, 2022). "In this line of research, elucidating the role of NRP1 in tumor development and progression has been addressed." (PMID 35884516, 2022). "Integrin αvβ3 is highly expressed in tumor tissues, whereas NRP-1 is widely expressed in both tumor and normal tissues, which weakens the tumor specificity of iRGE to a certain extent." (PMID 36199363, 2022). "EG3287 is a targeting polypeptide with the ability to specifically target Neuropihn-1 (NRP-1), which is a new target of tumor blood vessels." (PMID 35858896, 2022). "Our data further indicate that the expression of NRP-1 is lost over time in the tumor, and this can be at least partially explained by the failure to retain NRP-1+ Tregs." (PMID 35472220, 2022). "Since this discovery, investigations have been launched into the role of Nrp1 on T cell functioning within the context of tumor biology." (PMID 36203599, 2022). "The combination of PD-1 antibody and Nrp-1 antibody is more efficient in repressing tumor growth in vivo." (PMID 35155237, 2022). "NRP-1 increases angiogenesis (enhancing the production of pro-vascularization signals) and boosts the infiltration of Treg in the tumor mass while decreasing the number of T CD8+ lymphocytes and driving GAM polarization toward a pro-tumoral way." (PMID 35681612, 2022). "Otherwise, results evaluating the differential expression of NRP1 between tumor and adjacent tissue revealed a significant correlation between NRP1 overexpression and HCC pathogenesis upon analyzing patient subgroups." (PMID 35884516, 2022). "As major ligands for both NRP1 and NRP2 receptors, it is also conceivable that a loss of semaphorin signaling at least partially accounts for the reduced tumor growth exhibited by NRP1flflNRP2flfl.ECKO mice." (PMID 36970722, 2022). "Otherwise, NRP1 is broadly expressed in different tissues and increased levels of NRP1 have been observed in numerous tumor types, suggesting a potential role as an oncogenic protein." (PMID 35884516, 2022). "sNRP1 has previously been reported to inhibit the binding of VEGF to full-length NRP1, and both sNRP1 and sNRP2 have been shown to inhibit tumor angiogenesis and growth." (PMID 35653189, 2022). "Namely, function of regulatory T cells is maintained by NRP1—semaphorin pathway where T cell function and survival is potentiated at inflammatory sites where is is especially important to limit anti-tumour immune responses." (PMID 35955539, 2022). "Overexpression of neurofibrillary protein-1 (NRP-1) has been shown to be correlated with the invasive behavior of tumor cells." (PMID 36105933, 2022). "At present, research on NRP1 is involved in many fields such as angiogenesis, the hematopoietic system, immune system, and tumor occurrence and development." (PMID 35993027, 2022). "Imatinib in PLGA nanoparticles with NRP-1 targeting inhibited Treg cells in the tumor microenvironment, resulting in effective tumor immunotherapy." (PMID 37305347, 2022). "The results obtained so far suggest that integrins (particularly the integrin αvβ6) and neuropilin-1 are important receptors that mediate relevant pathophysiological functions of CgA and its fragments in angiogenesis, wound healing, and tumor growth." (PMID 36559048, 2022). "Taken together, these data strongly implicate NRP1 in claudin-low tumor progression and provide the preclinical rationale for future studies assessing NRP1 inhibition as a novel therapeutic strategy for this aggressive BrCa subtype." (PMID 35078508, 2022). "In vivo, MR438 was able to radiosensitize the DAOY tumors, which presented a high level of NRP1 positive cells as compared to other tumor models." (PMID 36457009, 2022).